KRAS (KRas proto-oncogene, GTPase)
Diseases named in the same sentence as KRAS in open-access papers (continued):
Sharing a sentence is not in itself a finding about the gene and the disease.
tumor (continued). "An emerging and exciting new direction may come from recent advances in our understanding of the relationship between KRAS mutations and tumor immune evasion." (PMID 36413402, 2023). "The benefits of nivolumab therapy in patients with NSCLC are related to tumor KRAS mutations." (PMID 37434177, 2023). "KRAS mutations were only related to tumor location in 369 CRC patients." (PMID 36862900, 2023). "Direct sequencing also confirmed that the KRAS point mutations detected in the ascites supernatant were identical to those found in ascites cell pellets, microdissected malignant cells from cytologic smears, and primary tumor tissues." (PMID 37007072, 2023). "In P6, the primary tumor was resected before the ctDNA test, and tissue KRAS mutation profiling was performed on the recurring/more advanced tumor of the primary site noted by image studies 7 months after the ctDNA test, returning a positive test result for KRAS p.G12V." (PMID 37511664, 2023). "Furthermore, the interplay between KRAS-associated pathways, including ferroptosis, and the tumor microenvironment, particularly the immune response, is of great interest." (PMID 38268915, 2023). "The correlation between tumor sidedness and KRAS mutations is highly controversial." (PMID 36899966, 2023). "In addition to inducing cell proliferation, KRAS mutations modulate the tumor microenvironment (TME) and alter the infiltration of immune cells and the expression of the cytokine expression." (PMID 37110848, 2023). "The tumor comprises subpopulations with different mutations (BRAF or KRAS) at its inception." (PMID 37958416, 2023). "Some features have been directly or indirectly linked to KRAS in promoting tumor progression." (PMID 37141389, 2023). "Moreover, while a preclinical study demonstrated KRAS mutation induced a more suppressive tumor microenvironment, RAS mutation was associated with an increased proportion of tumor‐infiltrating lymphocytes in the MSS group." (PMID 37081776, 2023). "KRAS is therefore one of the important tumor pathogenic genes." (PMID 37924117, 2023). "Brown tumour has been shown to be a neoplasia driven by KRAS-mutation." (PMID 37509363, 2023). "Tumor-cell-intrinsic KRAS mutations could orchestrate a network of immune suppression in tumor microenvironment (TME)." (PMID 37256126, 2023). "Furthermore, an increase in tumor-associated M2-macrophages (typically also activated against parasites) is present in KRAS mutant CRC compared to wild-type KRAS CRC38,39." (PMID 36707698, 2023). "In our research, out of 104 primary tumor samples of mCRC, 45.2% contained KRAS mutations." (PMID 37628868, 2023). "Pairwise comparisons indicated that the mean tumor size for the KRAS mutation-positive group was significantly larger than that of the ALK mutation-positive group (p = 0.01), which was significantly larger than that of the EGFR mutation-positive group (p = 0.001)." (PMID 37508989, 2023). "While existing literature hints at a significant association between KRAS mutations and a heightened immunogenicity within the tumor and inflammatory microenvironment, suggesting a potential favorable response to ICI therapy, the precise impact on prognosis remains inadequately elucidated." (PMID 37954616, 2023). "In addition, similar apoptosis was found in tumor‐specific CTLs from tumors with different types of KRAS mutations, suggesting that their AICD sensitivity was irrespective of KRAS mutation type." (PMID 36599679, 2023). "The second most common KRAS-mutated human tumor is CRC, which is resistant to chemoradiation." (PMID 36313934, 2023). "However, anti‐EGFR targeted treatments are ineffective in tumours with activating mutations in KRAS, NRAS and BRAF." (PMID 37604687, 2023).
tumor (continued). "Validation studies are needed, however KRAS mutation testing may have a role in assisting in diagnosis in patients with early pancreatic cancer with sufficient tumour tissue on endoscopic ultrasound." (PMID 37460806, 2023). "Patients with KRAS mutations showed a higher level of CD47 expression on the tumor cell surface." (PMID 36413402, 2023). "In addition, the levels of oncogenic KRAS determine the growth dynamics and aggressiveness of cancer cells with other mutations, such as Lkb1 (the third most frequently mutated tumour suppressor in human lung adenocarcinoma)." (PMID 36175301, 2023). "Combining independent risk factors from multivariate analysis, including ROS1 gene mutations, KRAS gene mutations, tumor stage, and endocrine system disease history, a new Nomogram was constructed to predict the therapeutic efficacy of ICIs immunotherapy in PD-L1 positive patients." (PMID 37468609, 2023). "Subsequently, we set out to investigate whether tumor‐infiltrating cytotoxic CD8+ T‐cells were linked to KRAS expression levels." (PMID 36599679, 2023). "Additionally, in lung cancer, the KRAS p.G12C mutation is associated with high Tumor Mutational Burden (TMB) and high PD-L1 expression, suggesting potential increased sensitivity to immunotherapy." (PMID 37509241, 2023). "Currently, there is intense research on how KRAS mutations in particular, in conjunction with other genetic alterations, may influence tumor infiltration of immune cell populations." (PMID 37370686, 2023). "The average GA/tumor was 4.88 for KRAS mutated and 4.47 for KRAS wild type." (PMID 37404765, 2023). "The transduced PBLs could recognize multiple HLA-A*11:01(+) tumor lines bearing the appropriate KRAS mutations." (PMID 37669923, 2023). "Among the 19 patients who developed benign tumours, only one (6%) carried somatic variant in KRAS, 16 (84%) showed a mutated HRAS allele, and two (10%) had mutations in PIK3CA genes; the 13 patients with cancer harboured somatic variants exclusively in the KRAS (31%) and HRAS (69%) genes." (PMID 37636262, 2023). "Understanding the mutational mechanisms of KRAS and delving into the role of different KRAS mutations in various tumor types present an intriguing challenge that can enhance our approach to agnostic therapies in oncology, with the inhibition of KRAS p.G12C serving as an example." (PMID 37509241, 2023). "Current trends have been focused on understanding the mutational and immune landscape of KRAS-mutant tumours to elucidate potential resistance mechanisms and immune modulatory niches that might be rationally exploited." (PMID 36864508, 2023). "Recent studies have indicated a correlation between CT texture features tumours characteristics that reflect tumour grade, cellular processes (e.g. hypoxia or angiogenesis) and genetic markers such as KRAS or epidermal growth factor receptor (EGFR) mutation status." (PMID 36620843, 2023).
tumor (continued). "Mechanistic investigations showed mutant KRAS‐driven lactic acid increased the susceptibility to AICD of tumor‐specific cytotoxic T‐cells via NF‐κB inactivation, which might underlie the correlation between KRAS status and intratumoral cytotoxic CD8+ T‐cells." (PMID 36599679, 2023). "KRAS-mutated proteins present neoantigens with high immunogenicity potential, and vaccines could offer a very specific anti-tumor effect." (PMID 37894382, 2023). "Furthermore, we found that high tumor NOX1 mRNA expression was associated with WT KRAS while both low ADAM17 and MCAM mRNA expression was associated with mutated KRAS." (PMID 38137406, 2023). "KEAP1 and STK11 mutations are associated with positive survival impact in KRAS-WT tumours." (PMID 36864508, 2023). "Moreover, G12D-specific inhibitors are already under investigation in phase I trials (e.g., NCT05382559); therefore, collecting more information about patients with tumours harbouring this specific KRAS mutation is of interest." (PMID 37297026, 2023). "It has been proven that the inhibition of phosphorylated ERK1/2 level in tumor cells with KRAS mutations may cause wide-type RAF phosphorylation and further result in activation of MEK, thereby restoring pERK level quickly and acquiring rebound." (PMID 37808191, 2023). "We first identified tumor cells within our ECs by calling KRAS p.Gly12Asp mutations." (PMID 37127830, 2023). "However, due to poor tumor cellularity in sampling biopsy and intratumor heterogeneity, false-negative results pose challenges to pathologists and clinicians in KRAS mutations detection." (PMID 38087207, 2023). "Tumor development is initiated by KRAS mutation at the earliest stages of pancreatic tumorigenesis." (PMID 37470859, 2023). "Another interaction example was tumours with KRAS mutations that showed CMS-specific responses." (PMID 37666855, 2023). "Therefore, lung cancer cells with simultaneous LKB1 inactivation and KRAS mutation are likely to exhibit greater glucose uptake and consumption, contributing to their rapid tumor growth and suppression of intratumor effector T-cell activity." (PMID 37675220, 2023). "As expected, KRAS-mutated cells presented with earlier tumor onset than KRAS WT cells." (PMID 36443441, 2023). "Surprisingly, the KRAS G12C mutation in the Polish population occurred more frequently in distal tumours, contrary to a known predisposition of RAS mutations for the proximal part of the colon and data on KRAS G12C-mutated tumours in the Scandinavian population." (PMID 37240418, 2023). "Nonetheless, both driver gene variants (KRAS p.G12V, SMAD4 p.A39T) identified by bulk WES of this same sample were identified with high-quality read data and indicated 113 likely tumor cells (23.6% of all) captured for this sample based on the presence of the clonal KRAS variant." (PMID 36765116, 2023). "In addition to acting as a message sender in communications with other cell types, KRAS mutated tumor cells also present some unique characteristics as a receiver." (PMID 38097680, 2023). "In addition, those with metastatic colon cancer should have tumor somatic genotyping for KRAS, NRAS, and BRAF mutations." (PMID 35837788, 2023).
tumor (continued). "To quantify the number and size of the tumors in each mouse, and to better understand the dynamics of lung tumor growth driven by these different oncogenic KRAS variants, we performed Tuba-seq on DNA extracted from bulk tumor-bearing lungs from mice across the different titers and timepoints." (PMID 37828026, 2023). "Similarly, the same trend was discovered regarding primary tumor locations and KRAS mutation status." (PMID 37064111, 2023). "Importantly, KRAS mutated tumor resistance to immunotherapies can be overcome by inhibiting KRAS or blocking lactic acid production." (PMID 36599679, 2023). "On these grounds, we hypothesized that mutant KRAS‐driven lactic acid might contribute to AICD susceptibility of tumor‐specific CTLs in KRAS mutant CRC." (PMID 36599679, 2023). "However, the prognostic value of low-frequency plasma circulating tumor DNA (ctDNA) KRAS mutation in predicting treatment resistance in pretreated mCRC patients remains controversial." (PMID 37511664, 2023). "Indeed, when size was compared at 6 months to baseline, different patterns were observed ranging from an increase in tumor size to a decrease in tumor size, patients harboring KRAS mutation being in the first case." (PMID 37524705, 2023). "A monoclonal antibody antagonist, Ab3-8, has been developed that recognizes the extracellular domain of ASCT2, reduces cellular glutamine import and Akt/ERK phosphorylation in SW1116 and HCT116 human CRC cell lines containing mutated KRAS, and inhibits the growth of tumor xenografts in mice." (PMID 36959802, 2023). "Additionally, two patients harboured a KRAS mutation in CTCs, which is dissimilar to the matched primary tumours." (PMID 37761948, 2023). "Interestingly, in contrast to tumor acquired KRAS mutations which predict cetuximab resistance, patients with the KRAS-variant have repeatedly been shown to respond favorably to cetuximab alone or in combination with chemotherapy." (PMID 37728512, 2023). "Here, we demonstrate that high tumor expression of the core autophagy gene ATG16L1 is associated with poor clinical response to anti-PD-L1 therapy in KRAS-mutant tumors from IMblaze370 (NCT02788279), a large phase III clinical trial of atezolizumab (anti-PD-L1) in advanced metastatic MSS-CRC." (PMID 37741832, 2023). "However, patients with a mutation in exon 4 of KRAS were 3.23 times more likely to have a tumor in the rectum than in other locations (95% CI: 1.19–8.72, p = 0.021)." (PMID 37628934, 2023). "Furthermore, KRAS is responsible of an immunosuppressive tumor microenvironment within mutated tumors in a PD-L1 dependent manner, and the effect of MRTX849 was diminished when CT26 KRASG12C+/+ were grown in T cell deficient nude mice." (PMID 37907934, 2023). "We showed that most of the internalized anti-KRAS antibodies are localized in the cytoplasm and not endosomes, and that the antibody altered endogenous KRAS localization from the inner plasma membrane to the cytoplasm in tumor cells harboring KRAS p.Gly12Val mutation." (PMID 37051535, 2023). "Of note, KRAS G12C-mutant tumors are commonly associated with tobacco exposure and exhibit higher tumor mutational burden, which might predict better responses to IT." (PMID 37916173, 2023). "Genetic approaches have demonstrated that KRAS mutations occur in over 95% of PDAC tumours." (PMID 37790705, 2023). "Unlike in NSCLC, single-agent activity seems to be more limited in KRAS-mutated CRC, lending credence to the hypothesis that other mutations or pathways could be bypassing direct KRAS inhibition and driving tumor growth." (PMID 37569406, 2023). "We next investigated whether cytotoxic CD8+ T‐cell tumor infiltrates correlated with a specific KRAS mutation type." (PMID 36599679, 2023).
tumor (continued). "In neither model we could identify any mutation selected or arising in the resistant tumour in comparison to the untreated control tumour beyond the known pre‐treatment KRAS mutation." (PMID 37604687, 2023). "KRAS mutation could upregulate the expression of PD-L1 in tumor cells by different mechanisms including improving the stability of PD-L1 mRNA, promoting ROS production and inducing FGFR1 expression in lung cancer." (PMID 38097680, 2023). "Thus, the compound was active in the low nanomolar range in both wild-type, and BRAF- and KRAS-mutated tumor models in vitro and in vivo." (PMID 37830744, 2023). "Since the concordance level in KRAS mutational status between tumor tissue and ctDNA is high (∼92%), the detection of KRAS mutations in ctDNA has been proposed as a rapid and minimally-invasive alternative method to tissue biopsy for predicting the response to anti-EGFR treatment." (PMID 36831626, 2023). "KRAS expression levels were associated with good prognosis and tumor progression." (PMID 38206735, 2023). "Subgroup analyses, e.g., by clinicopathological features (e.g., tumor stage) or molecular features (e.g., specific KRAS codon mutations), could potentially reveal an overlooked association." (PMID 36900260, 2023). "Moreover, KRAS-activating mutations can inhibit the apoptosis of tumor cells, modulate cell metabolism, and alter the tumor microenvironment to induce tumor immunosuppression, thus further promoting the metastasis of the tumor." (PMID 37110848, 2023). "Further studies have also been conducted in KRAS mutant tumors, and data shows that KRAS mutations may reshape the tumor immune microenvironment." (PMID 36675641, 2023). "The loss of HES1, a canonical Notch signaling target, may cooperate with KRAS mutations to remodel the extracellular matrix and to suppress the anti-tumor immune response." (PMID 36824959, 2023). "Then, we matched their results with the results of KRAS mutations detected in primary tumours." (PMID 37761948, 2023). "Additionally, mutations in PIK3CA, FAM123B and KRAS were only associated with right-sided tumours (FDRmol < 0.05, hypergeometric test)." (PMID 37666855, 2023). "A classic example was given: two tumours were subjected to targeted sequencing using a panel of 410 genes, one located in the pancreas (n=8 mutations) and one in lung (n=9 mutations), whereby they shared only one mutation, KRAS G12C." (PMID 35109903, 2022). "In addition, KRAS expression levels were associated with tumor mutation burden (TMB) and microsatellite instability (MSI) in 14 and 8 tumors." (PMID 36330448, 2022). "The genome damage that has been associated with tobacco carcinogens and that is commonly seen with KRAS G12C mutations may provide alternative pathways to drive tumor growth." (PMID 35267628, 2022). "This indicates that mutations in KRAS may have a greater impact on actively dividing tumor cells than on quiescent tumor cells." (PMID 35974387, 2022). "Furthermore, we detected a mismatch between the tumor cellularity and the allelic ratio of the KRAS G12C mutation in 24.3% of cases, suggesting that, at the cellular level, the mutation is heterogeneously present among tumor cells." (PMID 35205778, 2022). "Patients with loss of LKB1 with KRAS or EGFR mutations denote an aggressive tumor phenotype, that might be due to the loss of LKB1 as a metabolic sensor; these patients might benefit from biguanide treatment." (PMID 35890085, 2022). "KRAS co-mutation status may also impact the tumour microenvironment and the effect of immune checkpoint inhibition." (PMID 36284306, 2022).